CTNNB1 (catenin beta 1)
Diseases named in the same sentence as CTNNB1 in open-access papers (continued):
Sharing a sentence is not in itself a finding about the gene and the disease.
colorectal cancer (continued). "Further fine-mapping and functional analyses are required to identify the potential causative SNPs and to understand the roles of APC/CTNNB1 in colorectal cancer progression." (PMID 23405266, 2013). "Genetic mutations of the Wnt/β-catenin signalling intracellular components APC, CTNNB1 (β-catenin encoding gene), and Axin2 are major contributing factors for colorectal cancers." (PMID 23209942, 2012). "In cancer contexts such as colorectal cancer where upregulated WNT/β-catenin is mediated by constitutively activating downstream mutations in CTNNB1 or APC, therapeutic approaches to modulating WNT/β-catenin signalling have been somewhat limited." (PMID 23129487, 2012). "Homozygous mutation as detected by direct DNA sequencing of CTNNB1 seems to be uncommon in other neoplasms, but have been described in a rectal carcinoid tumor and in colorectal cancer." (PMID 18541010, 2008). "In conclusion, this study shows that mutations in the CTNNB1 gene are presumably of minor importance in sporadic colorectal cancer." (PMID 16356174, 2005). "In this study, the occurrence of mutations in the APC, CTNNB1 and K-ras genes as well as expression of the hMLH1 protein in tumour tissue of 656 sporadic colorectal cancer cases were investigated." (PMID 16356174, 2005). "Description of patient, tumour and molecular characteristics of colorectal cancers harbouring a CTNNB1 mutation." (PMID 16356174, 2005). "Notably, DCRGs showed a high mutation frequency in colorectal cancer and melanoma, with CTNNB1 having the highest mutation frequency in hepatobiliary cancer (23.7%) and uterine endometrioid carcinoma (20.8%)." (PMID 37033970, 2023). "Moreover, somatic APC mutations are found in more than 80% of colorectal cancers, but only approximately 5% of colorectal cancers harbor CTNNB1 mutation." (PMID 36428715, 2022). "The hot-spot mutations in exon 3 of CTNNB1, which might change the phosphorylation status of β-catenin, were mainly presented in colorectal cancer and other cancers." (PMID 34493320, 2021). "Moreover, mutations in CTNNB1 are related to several human malignancies, such as colorectal cancer, lung cancer, HNSC, and KIRC, although it is a rarely mutated gene." (PMID 32411180, 2020). "It is interesting that the low BMI subtype has low CTNNB1 mutation frequency in LIHC, and the high BMI subtype has high CTNNB1 mutation frequency and the effects of the WNT-CTNNB1 pathway alterations on colorectal cancer outcome are modified by BMI and physical activity." (PMID 32999719, 2020). "Interestingly however, evidence for selection of APC mutations above CTNNB1 mutations was found in colorectal cancer only." (PMID 29748584, 2018). "However, the exact molecular mechanism for the regulation of the Pygo and Bcl9 co-factors and their role in Apc- or Ctnnb1-associated colorectal cancer requires further analyses." (PMID 27811361, 2016). "HCT116 cells, isolated from colorectal carcinoma, are heterozygous for an activating mutation in CTNNB1 (ΔS45) that prevents it from being phosphorylated by casein kinase 1 alpha (CSNK1A1), which normally marks the protein for further phosphorylation and proteasomal degradation." (PMID 27333864, 2016). "In light of the critical role of the Wnt/APC/CTNNB1 signaling pathway in maintaining proper colorectal cell function, it is possible that genetic variants in this pathway might affect colorectal cancer progression." (PMID 23405266, 2013). "However, there have been no studies addressing the relation of common genetic variants in Wnt/APC/CTNNB1 pathway genes to clinical outcomes of colorectal cancer." (PMID 23405266, 2013). "In colorectal cancer cells with inactivating APC hemizygous mutation or activating CTNNB1 heterozygous mutation, the total β-catenin signaling activity seemed dependent also on silencing of SFRP genes by promoter hypermethylation with consistent constitutive WNT signaling." (PMID 18541010, 2008).
colorectal cancer (continued). "In five colorectal cancers, a CTNNB1 mutation that would lead to loss of one of the Ser/Thr phosphorylation sites and subsequent stabilisation of the protein, occurred at codons 37 and 45, all were C→T transitions, leading to Ser→Phe amino acid changes and occurred in the proximal colon." (PMID 16356174, 2005). "CTNNB1 mutations seem to be of minor importance in sporadic colorectal cancer." (PMID 16356174, 2005). "However, how gastric tumors achieve WNT niche independence remains unclear, as mutations on APC or CTNNB1—common mechanisms of ligand-independent WNT activation in colorectal cancer—are infrequent in gastric cancer." (PMID 41398956, 2025). "In addition, high expression of CTNNB1 is associated with shorter survival in colorectal cancer." (PMID 33723286, 2021). "The most prevalent genetic changes in colorectal cancers are biallelic APC mutations; less frequently, the WNT pathway may be activated in colorectal cancers by another genetic mechanism consisting of the gain-of-function mutations of the gene encoding β-catenin (CTNNB1)." (PMID 29652830, 2018). "However, these functions are likely dependent on the experimental system since c-Jun expression was also not required for proliferation of small intestinal epithelial cells upon knockout of Apc or an activating mutation of Ctnnb1 as well as during colitis-associated colorectal cancer." (PMID 22792392, 2012). "Mutations in APC and CTNNB1 are two major factors for Wnt/β-catenin signaling activation in colorectal cancers, however recent studies indicate that the levels of Wnt/β-catenin signaling in colorectal cancer cells could be modulated on the cell surface." (PMID 22195040, 2011). "The three other genes of the pathway that are frequently mutated in colorectal cancer samples, RNF43, CTNNB1, and TCF7L2, were also frequently mutated in colorectal cancer cell lines, although less frequently than APC." (PMID 40061138, 2025). "In colorectal cancer, breast cancer and hepatocellular cancer, the activation of the Wnt/β-catenin pathway leads to a worse overall survival as high levels of CTNNB1 promotes metastasis and epithelial-mesenchymal transition (EMT)." (PMID 40130164, 2025). "For example, MEF2A promoted tumor proliferation and metastasis by transcriptionally upregulating the expression of ZEB2 and CTNNB1 in colorectal cancer." (PMID 40066751, 2025). "circAURKA suppressed the degradation of CTNNB1 protein by facilitating the interaction of ACLY with CTNNB1 protein, accelerating the growth and metastasis of colorectal cancer." (PMID 39858034, 2025). "In colorectal cancer research, single-cell sequencing has revealed the abnormal activation of key signaling pathways, the Wnt-catenin beta 1 (CTNNB1/β-catenin) and phosphoinositide 3-kinase (PI3K)–protein kinase B (AKT) pathways." (PMID 41359105, 2025). "Our study shows that new target proteins involved in cancer and inflammatory responses, such as CTNNB1, become a biomarker for exercise anticancer effects in colorectal cancer and contribute to skeletal myopathy in heart failure via direct interaction FoxO." (PMID 40435272, 2025). "(A) Schematic representation of ieCTNNB1 (pink shading) and CTNNB1 promoter (yellow shading), which is respectively marked by H3K27ac and H3K4me3 peaks, and mRNA signals in native and tumor tissues of a patient with colorectal cancer." (PMID 39320349, 2024). "ieCTNNB1 is activated in colorectal cancer and its activity positively correlates with the expression of CTNNB1." (PMID 39320349, 2024).
colorectal cancer (continued). "MiR-520h can be sponged by PART1 to overexpress CTNNB1, thereby regulating the development of colorectal cancer." (PMID 38394156, 2024). "Optimal modulation of Wnt pathway activity seems critical to colorectal cancer survival, as overexpression of CTNNB1 in APC-mutant cell lines is synthetically lethal." (PMID 39324706, 2024). "Right: correlation between H3K4me3 signals at CTNNB1 promoter and CTNNB1 expression in native and tumor tissues of colorectal cancer patients (n=38)." (PMID 39320349, 2024). "The two top genes, which are much more essential in colorectal cancer cells than in other cancer types, were CTNNB1 and KLF5." (PMID 38622679, 2024). "(A) Chromatin immunoprecipitation sequencing (ChIP-seq) tracks of indicated trans-acting factors enriched at ieCTNNB1 (pink shading) and CTNNB1 promoter (gray shading) in indicated colorectal cancer cell lines." (PMID 39320349, 2024). "(B) Comparison of CTNNB1 expression levels in native and tumor tissues of colorectal cancer patients (n=68)." (PMID 39320349, 2024). "Right: comparison of H3K4me3 signals at CTNNB1 promoter in native and tumor tissues of colorectal cancer patients (n=42)." (PMID 39320349, 2024). "Similar to human colorectal cancer, overactivation of the WNT signaling pathway is also present in canine colorectal cancer, accompanied by repeated mutations in genes associated with CTNNB1 and TGF-β signaling pathways." (PMID 38098990, 2023). "Splicing in APC and in-frame deletions in Catenin beta 1 (CTNNB1) leading to oncogenic Wnt pathway activation were found in 96% of colorectal-cancer tumors." (PMID 36672698, 2023). "For instance, TRAF6 (TNF receptor associated factor 6) promotes the interaction between LC3B and CTNNB1 through the ubiquitination of LC3B and promotes the selective autophagic degradation of CTNNB1, inhibiting colorectal cancer metastasis." (PMID 37740194, 2023). "The CTNNB1 gene emerged as a factor of viability in colorectal cancer (Supertarget) and, to a lesser extent, in stomach cell lines." (PMID 37297004, 2023). "The study indicated that TRAF6 promoted the recognition and selective autophagic degradation of cis-acting circRNA generated by β-catenin (CTNNB1) by interacting with LC3 in colorectal cancer cell lines." (PMID 38016969, 2023). "Aberrant WNT hyperactivation (through stabilizing mutations in ß-catenin (CTNNB1), or in the adenomatous polyposis coli, APC, gene) is particularly common in colorectal cancer (CRC = COAD + READ), and is a major driver of CRC development." (PMID 37268816, 2023). "When analyzing the differential gene dependencies within the DepMap project, we found that Wnt‐high colorectal cancer cell lines were more dependent on CTNNB1 and other members of the Wnt signaling pathway than Wnt‐low colorectal cancer cell lines." (PMID 35904277, 2022). "This highlights the importance of the Hippo/YAP pathway in RNF43-mutant pancreatic cancer and is consistent with the observation of YAP dependency in APC/CTNNB1-mutant colorectal cancers." (PMID 35536676, 2022). "Research shows that over-expression of CTNNB1 promotes metastasis of colorectal cancer and colon cancer." (PMID 35783357, 2022). "CTNNB1 is a prognostic marker in colorectal cancer, a cancer-related gene, and a cancer biomarker candidate." (PMID 35268705, 2022). "Regarding CTNNB1, the frequency of alterations in colorectal cancer is roughly 10-fold higher than in breast cancer (5 vs. 0.6%)." (PMID 35663403, 2022). "According to the study, the knockdown of ALDH1B1 in colorectal cancer cells resulted in a reduction in CTNNB1 (β-catenin) mRNA levels." (PMID 34769507, 2021).
colorectal cancer (continued). "It has been found that miR-4262 can be sponged by circAGFG1, and it can regulate the YY1/CTNNB1 axis to drive colorectal cancer metastasis." (PMID 33821195, 2021). "The mRNA levels of CPEB4, APC, TRIP13, EIF2S3, EIF4A1, IFNg, PIK3CA and CTNNB1 genes expressed in colorectal cancer tissue specimens, colorectal cancer blood samples, normal colon tissues and blood samples were analysed." (PMID 33237662, 2021). "The aim of the study is to assess expression levels of CPEB4, APC, TRIP13, EIF2S3, EIF4A1, IFNg, PIK3CA and CTNNB1 genes in tumors and peripheral bloods of colorectal cancer patients in stages I–IV." (PMID 33237662, 2021). "Wnt signaling activation in colorectal cancer is induced mainly by APC (73%) and CTNNB1 (5%) mutations, suggesting that canonical Wnt/β-Catenin signaling is the leading form of Wnt signaling in colorectal cancer." (PMID 33234169, 2020). "The vast majority of colorectal cancers have mutations in Wnt pathway genes like adenomatous polyposis coli (APC) and β-catenin (CTNNB1)genes." (PMID 34803252, 2020). "And miR-214 was also demonstrated to target CTNNB1 in human cervical and colorectal cancer cells and 3T3-L1 pre-adipocyte." (PMID 32692763, 2020). "The seven significant colorectal cancer associated genes shortlisted from the differentially expressed genes were CALD1, CTNNB1, CXCL14, PTCH1, CXCL8, TNFAIP3, and NNMT after mapping with PubMed, OMIM, MeSH, and PMC databases." (PMID 32523911, 2020). "In colorectal cancer, an early mutation leading to such features usually occurs in the APC or CTNNB1 genes, thereby activating Wnt signalling." (PMID 33292279, 2020). "The unambiguous genetic evidence from human tumors leaves little doubt about the relevance of aberrant WNT/CTNNB1 signaling in the initiation and progression of colorectal cancer." (PMID 32083079, 2020). "To this regard, we observed in a previous work that ZFP36 expression in colorectal carcinoma cell lines is inversely correlated to Wnt/CTNNB1 pathway activity." (PMID 32784485, 2020). "Our data in colorectal cancer cell lines, suggests that downstream induction of the WNT pathway by activating mutations in CTNNB1 are sufficient to overcome the effects of TNKS blockade." (PMID 31891587, 2019). "Our observations also analyzed the grade of β-catenin protein of the CTNNB1 gene in colorectal cancer in Pakistani population." (PMID 31699039, 2019). "When APC and CTNNB1 mutations were compared, there was evidence for selection of CTNNB1 mutations over common APC mutations in each of liver cancer, uterine carcinoma, prostate cancer and colorectal cancer." (PMID 29748584, 2018). "We identified the genes involved in the colorectal cancer metastasis signaling pathway, such as CTNNB1, WNT, JAK, and AKT." (PMID 30453668, 2018). "PI3KCA mutation in colorectal cancer is associated with phosphorylated AKT expression, CTNNB1 inactive status and KRAS mutations." (PMID 29652830, 2018). "Wnt signaling has been widely implicated in cancer, especially colorectal cancer, in which mutation of key regulatory factors of the Wnt pathway (mainly APC and CTNNB1), was found in ninety percent of tumors, resulting in activation of the Wnt pathway." (PMID 29515771, 2018). "NCB-0846 inhibited the TCF/LEF transcriptional activity of Wnt3a-treated HEK293 and HCT116 (carrying CTNNB1 mutation) and DLD-1 (carrying APC mutation) colorectal cancer cells." (PMID 27562646, 2016).
colorectal cancer (continued). "Over 94% of colorectal cancer cells have mutations in one or more members of the Wnt signaling pathway, of which 80% of sporadic colorectal cancers are associated with mutation of APC and 10% with mutation of CTNNB1, the gene encoding the protein of β-catenin." (PMID 26862734, 2016). "In light of these observations, we wanted to investigate the specific function of TCF7L1 in colorectal cancer models to determine how it regulates cell proliferation, tumor growth, and CTNNB1/TCF target gene expression." (PMID 27333864, 2016). "In contrast to sporadic colorectal carcinomas, in which the majority harbors APC, CTNNB1 or KRAS mutations, colorectal carcinomas that arise in the setting of chronic inflammatory diseases have a very low frequency of these mutations." (PMID 26744320, 2016). "In colorectal cancer cells, frequent mutations are observed in APC, the responsible gene for familial adenomatous polyposis of the colon, and β-catenin (CTNNB1)." (PMID 24466159, 2014). "We assessed the use of tag single nucleotide polymorphisms (tSNPs) in adenomatous polyposis coli (APC)/β-catenin (CTNNB1) genes to predict outcomes in patients with colorectal cancer." (PMID 23405266, 2013). "Notably, APC‐derived mutations were predominantly observed in colorectal cancer (18.6%, 11/59), while TERT promoter and CTNNB1 mutations were most found in liver cancer, with detection rates of 34.5% (10/29) and 24.1% (7/29), respectively." (PMID 39748775, 2025). "A previous study reported that CTNNB1 is highly expressed in colorectal cancer." (PMID 37151391, 2023). "To test this hypothesis, we examined more colorectal cancer cell lines, including 6 other lines carrying mutations of either the APC tumour suppressor gene or the CTNNB1 (β‐catenin) gene." (PMID 35301819, 2022). "Another study elucidated that MEF2A could directly upregulate CTNNB1 and enhance the activity of Wnt/β-catenin signaling in colorectal cancer." (PMID 35477537, 2022). "Both the APC gene and CTNNB1 are often mutated in colorectal cancers of non-FAP patients, and overexpression of constitutively active CTNBB1 or loss of APC function can result in colorectal tumorigenesis." (PMID 35207472, 2022). "Alternatively, point mutations of the β-catenin coding gene CTNNB1 lead to alterations in the protein’s N-terminal Ser/Thr phosphorylation sites, thereby preventing phosphorylation by GSK3β and consequent degradation in some APC wild-type colorectal cancers." (PMID 35663403, 2022). "Some genes do manifest this type of selectivity (e.g., broad dependence on CTNNB1 in colorectal cancer, MYB in leukemia, IRF4 in multiple myeloma, KRAS in pancreatic cancer, and SOX10 in skin cancer), but such common essentiality within a lineage is relatively unusual." (PMID 33554860, 2021). "Moreover, lncRNA PART1 is reported to function as a ceRNA to enhance CTNNB1 expression and activate Wnt/β-catenin pathway by competitively sponging miR-150-5p in colorectal cancer." (PMID 33680969, 2021).